PPARG (peroxisome proliferator activated receptor gamma)
Diseases named in the same sentence as PPARG in open-access papers (continued):
Sharing a sentence is not in itself a finding about the gene and the disease.
cancer (continued). "Compared to uninfected cancers, the infected cancers had significant upregulation of nine cellular factors (FCER2, MS4A1 (CD20), PLUNC, TNFSF9, TRAF1, CXCL11, IFITM1, PPARG, and FCRL3), implying that EBV is not an innocent bystander with respect to biochemical impact." (PMID 22929309, 2012). "However, the precise role and mechanism by which PPARγ regulates EMT and cancer metastasis are not yet well defined." (PMID 19884989, 2009). "Although the role of the HMGB1-RAGE axis in cancer is not completely clear, HMGB1 is critical for directly activating RAGE or activating peroxisome proliferator-activated receptor gamma (PPAR-γ) pathway, and inhibiting HMGB1-RAGE activation, which might be a beneficial cancer therapeutic strategy." (PMID 32660524, 2020). "Recently, non-genomic cross-talks between PPARγ and cytoplasmic proteins, like (extracellular signal regulated kinase) ERK 1/2, and (mitogen-activated protein kinase) MAPK kinases, have been reported in cancer cells and functional importance has been given to the subcellular localization of PPARγ." (PMID 19587804, 2009). "Therefore, clinical trials withcombination therapies were initiated to exploit PPARγ activation and simultaneousblockage of the promitotic and proinflammatory COX1/2-mediated eicosanoidproduction, which contributes to nongenomic signaling in cancer tissues." (PMID 18596912, 2008).
metabolic disorders (266 papers, 2007 to 2026). "Although PPARG is often targeted with agonists in metabolic diseases, our data indicates that high PPARG is associated with the aggressive, fibroblast-rich phenotype in OSCC." (PMID 41596281, 2026). "Severe hypothermia causes metabolic disorders in cerebral cortex nerve cells, significantly altering ferroptosis-related genes such as PPARG, SCD, ADIPOQ, SAT1, EGR1, and HMOX1." (PMID 39125656, 2024). "Mutations in PPARG can disrupt these regulatory mechanisms, potentially leading to metabolic disorders and increased cardiovascular risk." (PMID 38201926, 2023). "Variants in the PPARγ affect gene transcription and expression, which has been intensively studied in metabolic diseases." (PMID 36587194, 2022). "Numerous studies have revealed that two PPARγ gene polymorphisms (C1431T and Pro12Ala) are related with several metabolic disorders." (PMID 36292779, 2022). "It would also be of importance to further investigate the potential benefits of targeting PPARγ in preventing age-associated metabolic diseases and promoting longevity." (PMID 30186237, 2018). "PPARγ activation has been shown to promote the polarization of macrophages toward an anti-inflammatory M2 phenotype, helping to inhibit chronic inflammation and mitigate diseases associated with metabolic disorders." (PMID 40732928, 2025). "PPARG (peroxisome proliferator activator receptor gamma), a ligand-activated transcription factor affecting fatty acid oxidation and lipid metabolism, is implicated in metabolic disease (e.g., obesity and diabetes)." (PMID 36768972, 2023). "Due to its role in macrophage polarization and regulation of inflammation, PPARγ has become an attractive pharmacological target for the development of drugs used for the treatment of metabolic disease in which activated macrophages play prominent pathogenic roles." (PMID 33260769, 2020). "Interestingly, two miRNAs targeting PPARα (miR-21 and miR-519d) and two miRNAs targeting PPARγ (miR-27 and miR-20) were also previously associated with metabolic diseases." (PMID 28167956, 2017). "The rs5219 SNP—which causes the K23E substitution in KCNJ11 gene —maps to the consensus of the nuclear receptor PPARγ, and it is predicted to alter the binding affinity of this TF, a crucial player in glucose and lipid homeostasis and that is associated with metabolic disorders." (PMID 27347941, 2016). "FKBP51 has been implicated in metabolic disorders through its modulation of the insulin receptor pathway and its correlation with leptin signaling, as well as by interacting with peroxisome proliferator-activated receptor-γ (PPARγ) and regulating the energy sensor AMPK." (PMID 39596380, 2024). "Hence, defects in PPARγ have been associated to the development of metabolic disorders." (PMID 38874666, 2024). "HFD-fed hCYP2B6-Tg male and female mice were less susceptible to the development of metabolic disease compared to Cyp2b-null mice through different mechanisms as female mice showed reduced body weight and males increased glucose sensitivity consistent with PPARγ activity." (PMID 36520866, 2022). "Since the canonical function of PPARγ is the regulation of glucose and lipid metabolism, it is more than probable that these phenotypes were caused by the impaired metabolism in these patients and not because the loss of PPARγ contributed to an enhanced inflammation in metabolic disease." (PMID 21382489, 2011). "The many pathologic effects of LPA in the lung include the co-suppression of peroxisome-proliferator-activated receptor γ (PPARγ), a therapeutic target in metabolic disorders." (PMID 42066771, 2026). "These insights highlight PPARγ's important role linking FA metabolism, peroxisomal and mitochondrial β‐oxidation and the development or prevention of metabolic disease." (PMID 40968591, 2025). "This reciprocal regulatory relationship underscores the therapeutic potential of targeting the PPARγ–PGC-1α axis in metabolic disorders." (PMID 41476922, 2025).
metabolic disorders (continued). "Drugs like TZDs, which act as PPARγ agonists, are used to improve insulin sensitivity and promote glucose uptake in tissues, further emphasizing the importance of PPARγ in metabolic disease management." (PMID 40926269, 2025). "Thiazolidinediones (TZDs) are a class of PPARγ agonists that have long been used as insulin sensitizers and treatments for metabolic diseases, including MASLD." (PMID 40985048, 2025). "Anti-metabolic disorder therapies targeting PPARα and PPARγ include fibrates, TZDs, and dual agonists." (PMID 40985048, 2025). "Future studies are needed to investigate the regulation of PPARγ phosphorylation sites and their roles in metabolic diseases." (PMID 40985048, 2025). "Among these, PPARγ has emerged as one of the most promising targets for treating metabolic diseases such as NASH." (PMID 40994455, 2025). "Epigenetic histone modulations of PPARγ and related pathways contribute to olanzapine-induced metabolic disorders." (PMID 40124298, 2025). "It is worth noting that many of these dysregulated lipids are PPARG-regulated species, which are involved in oxidative stress, metabolic disorders, and other aspects, and are functionally related to the reduction of aging and apoptosis." (PMID 41305001, 2025). "PPAR activators, such as PPARγ agonists, have been used for metabolic disorders and improving cardiovascular outcomes." (PMID 41190023, 2025). "Inflammasomes interact with various metabolic regulatory pathways, including the mechanistic target of rapamycin (mTOR) and peroxisome proliferator-activated receptor gamma (PPARγ), highlighting the complexity of their roles in metabolic disorders." (PMID 40433411, 2025). "Together, the findings underscore the potential of dual PPARG-targeting approaches for metabolic disease interventions." (PMID 40564064, 2025). "Through these multiple mechanisms—lipid metabolism, glucose regulation, insulin sensitivity, and inflammation—PPARγ remains a critical target for managing metabolic diseases, particularly T2DM." (PMID 40926269, 2025). "These immune-modulatory effects of PPARγ suggest that it is not only a crucial player in managing metabolic disorders but also a promising therapeutic target for inflammation-driven conditions." (PMID 40926269, 2025). "Kaempferide improves glycolipid metabolism disorder by activating the PPARγ and its downstream signaling pathway." (PMID 40509282, 2025). "Beyond its role in adipocyte differentiation, PPARγ also improves lipid handling in adipose tissue, with therapeutic implications in metabolic diseases." (PMID 41009428, 2025). "PPARγ agonist, such as TZDs, has also been extensively used to treat metabolic disorders due to their potent insulin-sensitizing properties." (PMID 40985048, 2025). "PPARγ plays an important role in regulating lipid metabolism, the inflammatory response, and cell differentiation; therefore, PPARγ activators are commonly used to treat metabolic diseases." (PMID 40266913, 2025). "Activation of PPARγ promotes fat accumulation, whereas its inhibition has been shown to alleviate metabolic disorders." (PMID 41488302, 2025). "Our recent studies, alongside numerous others, have highlighted the pivotal roles of DNA methylation and histone modifications in the regulation of PPARγ and PPARα, implicating them in the deterioration of metabolic disorders via epigenetic mechanisms." (PMID 39595621, 2024). "The present review summarizes the available data on PPARγ and PPARα regulation via epigenetic mechanisms, elucidating the link between the development of metabolic disorders and the dysregulation of PPARγ and PPARα resulting from these mechanisms." (PMID 39595621, 2024). "Specific histone modifications have previously been correlated with divergent PPARG expression and the development of metabolic disorders." (PMID 39595621, 2024).
metabolic disorders (continued). "PPARγ is also considered to play a significant role in the pathogenesis of many diseases, particularly metabolic disorders and the epigenetic regulation of PPARG; in particular, DNA methylation has a significant impact, mainly by regulating PPARG expression." (PMID 39595621, 2024). "We also found an increase in the mRNA of peroxisome proliferator-activated receptor gamma, a very important target in lipid metabolism and metabolic diseases." (PMID 37108582, 2023). "In summary, this study further confirmed our previous report on the role of the histone modulation of the PPARγ pathway in olanzapine-induced metabolic disorders." (PMID 37298094, 2023). "Of note, several studies have demonstrated that dual PPARα and PPARγ agonists are effective for treatment of metabolic diseases including NAFLD in ob/ob mice and rats." (PMID 36172518, 2022). "Earlier studies on rabbits have shown that compounds isolated from CM fruit extract increase the expression of PPARA and PPARG receptors and indicate an important role of PPARG in the regulation of potential metabolic disorders." (PMID 35684107, 2022). "Nevertheless, this highlights PPARγ agonism as a therapeutic option for targeting NLRP3 inflammasome activation in NLRP3-related metabolic diseases." (PMID 33500734, 2021). "AhR regulates PPARγ stability and AhR–PPARγ interaction is a potential therapeutic target for metabolic diseases." (PMID 34432833, 2021). "The okra polysaccharides, mainly rhamnogalacturonan, can improve metabolic disorders via down-regulating PPARγ." (PMID 34966782, 2021). "Due to its role in adipocyte differentiation, lipid metabolism, glucose homeostasis, insulin sensitivity, and, more recently, in inflammatory and immune responses, PPARγ represents an attractive pharmacological target to address metabolic disorders." (PMID 32138197, 2020). "There have been attempts made to develop drugs that act on multiple PPARs including PPARα, PPARγ, and PPARδ for treating metabolic diseases." (PMID 33776749, 2020). "Accordingly, PPARγ agonist treatment rescued the activity of PPARγ, and restored the metabolic disorders in HFD-fed PPARγ3RA/+ mice." (PMID 32973516, 2020). "Through the last decades, several members of classical agonist families such as the fibrates (PPARα), the glitazones (PPARγ), and the glitazars (PPARα/γ) have been approved for the treatment of metabolic diseases in humans." (PMID 32695150, 2020). "The connection between alterations in the signaling pathways and metabolic diseases is particularly well-illustrated in the case of PPARγ." (PMID 30893897, 2019). "As partial agonists of PPARα and PPARγ, CoQ10, idebenone and other related benzoquinones have the potential to treat a variety of metabolic disorders." (PMID 30171034, 2018). "As PPARγ functions as a master regulator of fat cell differentiation and glucose/lipid metabolism, understanding the mechanisms of PPARγ regulation is crucial for combating metabolic disorders." (PMID 30323259, 2018). "Overall, although PPARγ has been recognized as a promising target in preventing and treating metabolic diseases, challenges remain in finding the suitable agonists with high therapeutic efficacy and low side effects." (PMID 30186237, 2018). "Taken together, these data indicate that TRIM25 is a novel E3 ubiquitin ligase of PPARγ and that TRIM25 is a novel target for PPARγ-associated metabolic diseases." (PMID 30323259, 2018). "From a therapeutic point of view, these results emphasize the need of personalized treatment when targeting PPARγ to treat metabolic disorders in patients of different ages." (PMID 30186237, 2018). "Understanding how PPARγ dynamically complexes with its cofactors to transactivating specific downstream target gene sets in different metabolic conditions might provide a novel angle in search of new therapeutic compounds against various aspects of obese- and aging-associated metabolic diseases." (PMID 30186237, 2018).
metabolic disorders (continued). "A previous paper suggested that PPARγ is involved in the restoration of metabolic disorder by propolis or kaempferol treatment." (PMID 29720160, 2018). "In this review, we discuss the dynamic components and precise regulatory mechanisms of the PPARγ-cofactors complexes in adipocytes, as well as perspectives in treating metabolic diseases via specific PPARγ signaling." (PMID 30186237, 2018). "Recently, several researchers reported ameliorating effects of pharmacological activators for these Nrf2 and PPARγ pathways on the progression of various metabolic disorders and drug-induced organ injuries by oxidative stress." (PMID 28928902, 2017). "From now on, therapeutic efficacies and toxicities of various Nrf2 and PPARγ activators studied in these metabolic disorders and some drug-induced organ injuries will be summarized first." (PMID 28928902, 2017). "PPARγ (Peroxisome proliferator-activated receptor γ) is a nuclear receptor involved in lipid homeostasis and related metabolic diseases." (PMID 28059128, 2017). "Comparing the findings from human and mouse PPARγ related metabolic diseases, we can conclude that mice models can generally be used to investigate and more deeply understand the processes of human diseases." (PMID 27483259, 2016). "They highlighted the complex function of PPARγ in cell differentiation, inflammation, glucose and lipid homeostasis pointing ahead its role in metabolic diseases." (PMID 27483259, 2016). "The peroxisome proliferator-activated receptor (PPARG) is a nuclear hormone receptor and plays an important role in obesity, insulin resistance, and other metabolic diseases as well as CHD." (PMID 28042567, 2016). "For this reason, an alternative approach for the treatment of metabolic disorders is represented by the development of partial PPARγ agonists or selective PPARγ modulators." (PMID 27708429, 2016). "PPARγ is one of three known isoforms, a regulator of lipid and glucose metabolism responsible for metabolic disorders and also act as the molecular target for drugs against several metabolic disorders." (PMID 27777867, 2016). "PPARγ is most highly expressed in adipose tissue, which has been demonstrated as a target for the treatment in metabolic diseases and cardiovascular diseases." (PMID 27171397, 2016). "Peroxisome proliferator-activated receptor gamma (PPARγ) is a key regulator of glucose and lipid metabolism and therefore an important pharmacological target to combat metabolic diseases." (PMID 23630612, 2013). "PPARγ agonists, such as the long chain fatty acid (FA) docosahexaenoic acid (DHA), improve metabolic disease in both human and animal models and increase PPARγ mediated transcription of targets such as adiponectin." (PMID 23533720, 2013). "PPARγ participates in mediating metabolic disorder via numerous downstream adipogenic and lipogenic genes, which are important for adipocyte maturation, lipid accumulation, and insulin-sensitive glucose transport, including FAS, ACC, aP2, SCD-1, and CD36." (PMID 23533476, 2013). "The well-established important role in the regulation of glucose and lipid metabolism renders PPARγ a valid pharmacological target for combating metabolic diseases." (PMID 23811337, 2013). "The important functions of PPARγ in the regulation of glucose and lipid metabolism make it an attractive pharmacological target for combating metabolic diseases." (PMID 23630612, 2013). "Collectively, the data indicate that rhein plays a role in metabolic disorders by regulating PPARγ signaling." (PMID 23049539, 2012). "A better understanding at the molecular level of the regulation of PPARγ/RXRα by their coactivators would benefit new therapeutic approaches for the treatment of metabolic diseases." (PMID 23319938, 2012). "This body of work is attractive since the interest for PPARγ modulation as a strategy to treat metabolic diseases has increased recently, due to better understanding of PPARγ action." (PMID 23125847, 2012).